LRRK2 (leucine rich repeat kinase 2)
Diseases named in the same sentence as LRRK2 in open-access papers (continued):
Sharing a sentence is not in itself a finding about the gene and the disease.
Parkinson disease (continued). "Using a combination of proteomics and imaging techniques, a study in HEK293T cells reported the function of LRRK2 in mediating endosome-TGN transport by scaffolding the GARP–SNARE interaction (VAMP4; STX6), suggesting a connection between GARP and LRRK2 in Parkinson’s disease." (PMID 37047041, 2023). "Interestingly, the variants in LRRK2 and NOD2 found in the twins had previously been identified as genetic modulators for risk of Parkinson’s and Crohn’s diseases with the two LRRK2 variants showing antagonistic pleiotropy." (PMID 36972292, 2023). "This has motivated the development of LRRK2 inhibitors as a putative Parkinson’s disease therapy." (PMID 37487100, 2023). "For 14-3-3γ to modulate the activity of LRRK2 and become a new strategy to treat Parkinson's disease, a better understanding of the functional network of 14-3-3γ and further research into the molecular processes of its interactions with key partners is required." (PMID 36604743, 2023). "Indeed, LRRK2 has been dubbed the ‘Rosetta stone’ of Parkinsonism, perhaps providing a common link between various neurological diseases." (PMID 37884687, 2023). "Of relevance, leucine-rich repeat kinase 2 (LRRK2), a kinase linked to genetic and sporadic Parkinson’s disease (PD), has been identified as a positive mediator of neuroinflammation upon different inflammatory stimuli, however its pathogenicity in AD remains mainly unexplored." (PMID 36830676, 2023). "Given that several LRKK2 variants increase LRKK2 kinase activity toward Rab10, an emerging new approach for disease modification in Parkinson’s disease is inhibition of the LRRK2-Rab signaling pathway and subsequently restoring normal membrane trafficking and lysosomal activity." (PMID 37156612, 2023). "In mouse melanocytes, which express high levels of Rab38, Rab32, and Rab29, knockdown (or CRISPR knockout) of Rab38, but not Rab32 or Rab29, decreases phosphorylation of multiple LRRK2 substrates, including Rab10 and Rab12, by both endogenous LRRK2 and exogenous Parkinson’s disease-mutant LRRK2." (PMID 37625589, 2023). "Our objective was to discriminate between Parkinson’s disease patients, i.e., those with and without a LRRK2 mutation, and healthy subjects." (PMID 37759704, 2023). "Selective inhibition of LRRK2 by MLi2, an ATP-competitive inhibitor induces rapid recycling of RAB10 vesicles, thus reducing endocytic defects caused by hyperactivation of LRRK2 signalling in a murine model of Parkinson disease." (PMID 36968200, 2023). "LRRK1 is related to the familial Parkinsonism gene product Park8 (LRRK2)." (PMID 36254578, 2022). "Leucine-rich repeat kinase 2 (LRRK2) is a potential target for treatment of Parkinson’s disease." (PMID 35011562, 2022). "The presence of multiple minor variants (p.S16478, p.R1628P, and p.G2385R) in the LRRK2 gene is usually correlated with a lower age at the Parkinson ́s disease onset—52.6 (±12.3) years—as compared to patients without these risk variants—62.5 years (±10.5)." (PMID 35054514, 2022). "In LRRK2-GS Parkinson's disease, there is a long preclinical stage where a carrier could be identified by genetic testing decades before he or she was symptomatic." (PMID 36388213, 2022). "Ser(P)-1292 LRRK2 protein was detected in exosomes from urine of Parkinson’s disease patients." (PMID 35336787, 2022). "Leucine-rich repeat kinase 2 (LRRK2) is one of the mostpromisingtargets for Parkinson’s disease." (PMID 36007011, 2022). "In addition, the authors discuss that these findings are contradictory to those found in familial forms of parkinsonism, particularly LRRK2 G2019S18 and several Parkin mutants, where mitochondrial depolarization has been observed." (PMID 35787292, 2022). "Results from this study will indicate whether LRRK2 inhibitors improve clinical measures such as the Unified Parkinson’s Disease Rating Scale (UPDRS)." (PMID 36358947, 2022).
Parkinson disease (continued). "Lastly, our models confidently separate LRRK2 and sporadic Parkinson’s disease lines from healthy controls (receiver operating characteristic area under curve 0.79 (0.08 standard deviation)), supporting the capacity of this platform for complex disease modeling and drug screening applications." (PMID 35338121, 2022). "Thus, we evaluated mitochondrial phenotypes in Parkinson’s disease patients’ fibroblasts carrying mutations in PINK (I368N), PARK2 (R275W), and the most common Parkinson’s disease gene, LRRK2 (G2019S)." (PMID 35326504, 2022). "The c.6055G>A transition in the leucine-rich repeat kinase 2 (LRRK2) gene results in the G2019S substitution in the LRRK2 protein, which is associated with familial, autosomal dominant forms of Parkinson’s Disease (PD) and represents a risk factor for idiopathic PD." (PMID 35453631, 2022). "Likewise, SNCA (α-synuclein), PARK2 (parkin), PARK7 (DJ-1), PINK1 and LRRK2 are the mutated genes of parkinsonism, among which mutations in both PARK2 (parkin) and LRRK2 are the most common genetic causes." (PMID 36478742, 2022). "LRRK2 is a protein kinase, a gene highly associated with Parkinson’s disease, and has not been studied in MS and EAE." (PMID 36341423, 2022). "Moreover, two Parkinson’s disease-related proteins, LRRK2 and DJ-1, have been identified in urinary and CSF exosomes." (PMID 33922446, 2021). "The LRRK2-related phenotype, closely resembling iPD, is characterized by a late-onset progressive Parkinsonism, with resting tremor as a common presenting feature, good response to levodopa therapy, and, usually, positive outcomes with deep brain stimulation (DBS)." (PMID 34630269, 2021). "These striking differences in neuropathological characteristics indicate that there are likely different disease modifiers of mutant LRRK2 or environmental modifiers that affect neurodegenerative trajectories of α-syn and tau pathology in LRRK2 parkinsonism in vulnerable cell populations." (PMID 33494262, 2021). "We have analyzed the effect of DNM3 rs2421947 on AAO in LRRK2 p.G2019S parkinsonism." (PMID 32873436, 2021). "This review explores how potential genetic and biochemical modifiers of LRRK2 function may contribute to the onset and clinical presentation of LRRK2 parkinsonism." (PMID 33494262, 2021). "In dopaminergic neurons differentiated from G2019S LRRK2-hiPSCs, mRNAs with complex secondary structure in the 5’-UTR are translated more efficiently, so some increased proteins induced by G2019S LRRK2 enhance calcium influx and contribute to the pathogenesis of Parkinson’s disease." (PMID 34759048, 2021). "Further studies that identify the mechanisms by which LRRK2 reduction promotes LUAD tumorigenesis have the potential to benefit cancer patients, and to inform the design of LRRK2 inhibition strategies in Parkinson’s disease that mitigate potential pulmonary-related adverse effects." (PMID 33483550, 2021). "However, a lysosomal centric explanation of cell death is insufficient to explain the increase in 4R tau for PSP and the increase in SND pathology in LRRK2 parkinsonism." (PMID 33494262, 2021). "Parkinson's causing D620N autosomal dominant mutation in the VPS35, the cargo binding subunit of the retromer complex also elevates LRRK2 mediated Rab protein phosphorylation through an unknown mechanism." (PMID 33367571, 2021). "Previously, research on LRRK2 were mainly focused on its role in Parkinson’s disease." (PMID 34217264, 2021). "The associations of LRRK2 G2019S and GBA genotypes on the rate of decline in Montreal Cognitive Assessment (MoCA) and Movement Disorders Society-Unified Parkinson Disease Rating Scale–Part III scores were examined using linear mixed effects models with PD duration as the time scale." (PMID 33881531, 2021).
Parkinson disease (continued). "Our finding of mitochondrial dysfunction controlled by excessive actin stabilization promoted by α-synuclein and LRRK dysfunction are consistent with prior findings in LRRK2-G2019S iPSC and more broadly with the strong implication of altered mitochondrial function in Parkinson’s disease." (PMID 34030727, 2021). "This difference in potency between wild type and pathogenic LRRK2 for Type II inhibitors would need to be taken into consideration when evaluating the optimal therapeutic doses of a potential future Type II inhibitor compound for treating LRRK2 driven Parkinson's disease." (PMID 34515301, 2021). "We then examined whether LRRK2 and Parkin recruitment to damaged mitochondria was impaired in 7 fibroblast lines of FTLD and parkinsonism patients or at-risk individuals with MAPT mutations, obtained from the NINDS human and cell repository." (PMID 34805172, 2021). "In sporadic conditions, the clinical presentation of LRRK2‐associated Parkinsonism is not different." (PMID 34291612, 2021). "LRRK2 was previously shown to negatively regulate protein kinase A activity in LRRK2-enriched striatal projection neurons (SPN), supporting a pathogenic mechanism of SPN dysfunction in Parkinson’s disease (PD)." (PMID 33466414, 2021). "Meta-analysis of the effect of VAMP4 rs11578699 (the genome-wide significant association in a recent large-scale PD GWAS) on AAO in LRRK2 p.G2019S parkinsonism was not significant for CC versus TT and TC genotypes (beta = −0.25, p = 0.75, n = 756))." (PMID 32873436, 2021). "Besides, PAK6 controls neurite complexity in the healthy brain and leucine-rich repeat kinase 2 (LRRK2), a causative gene for Parkinson’s disease (PD)." (PMID 33796531, 2021). "Interestingly, LRRK2 is involved in the regulation of p62-depenent autophagy, and it has been discussed as a druggable target for Parkinson's disease." (PMID 32070232, 2020). "The clinical manifestations of both patients are as typically seen in other PARK2 mutation carriers rather than in other LRRK2 mutation carriers, including dopa-responsive parkinsonism and an early age at onset." (PMID 32375870, 2020). "Viewpoint - is LRRK2 inhibition in Parkinson’s patients sufficient?" (PMID 33066808, 2020). "Midbrain-like simBOs from a Parkinson’s disease patient (LRRK2G2019S)-derived pNSCs and gene-corrected (LRRK2WT) control pNSCs represented disease-associated phenotypes in terms of increased LRRK2 activity, decreased dopaminergic neurons, and increased autophagy." (PMID 33195269, 2020). "Comparison of demographic and clinical characteristics of patients with Parkinson's disease by LRRK2 mutation status (LRRK2 carriers vs. patients without mutations in known Parkinson's disease-associated genes)." (PMID 32849182, 2020). "Alpha-synuclein protein, leucine-rich repeat kinase 2 (LRRK2), Parkinson disease protein 7 (PARK7), and DJ-1, as well as myocyte-specific enhancer factor 2D protein (MEF2D), which are dysregulated or mutated in Parkinson’s disease, are CMA substrates." (PMID 32792938, 2020). "Our findings demonstrate a selective but functional intersection between glucocerebrosidase dysfunction and LRRK2 signaling in the cell and may have implications in the pathogenesis and treatment of Parkinson’s disease." (PMID 32499675, 2020). "Autosomal dominant inherited mutations in genes including LRRK2 and GBA cause late onset PD with symptoms similar to sporadic PD, while autosomal recessive mutations in other genes such as PINK1 cause early onset forms of parkinsonism." (PMID 33126694, 2020). "For example, in neurodegenerative diseases, there is a significant proportion (>10%) of monogenic families in whom the disease is caused by singular highly penetrant disease genes, e.g., LRRK2 and PRKN in Parkinson’s disease or PSEN1 and APP in Alzheimer ́s disease." (PMID 32854198, 2020).
Parkinson disease (continued). "They found that LRRK2 mutations are associated with significantly increased cholinergic activity in the brain in mutation carriers without Parkinson's disease compared with healthy controls." (PMID 32457695, 2020). "Furthermore, variants within the LRRK2 and Rab29 genes synergistically increase Parkinson's risk, and studies in Caenorhabditis elegans indicated that RAB29 (GLO-1) ortholog acts upstream of LRRK2 (LRK-1) in a pathway controlling axon termination." (PMID 32036294, 2020). "At present, little is known about how Lrrk2 modifies the gene expression program induced by innate signaling pathways and how this might contribute to Parkinson's disease initiation and progression." (PMID 32111741, 2020). "Leucine rich-repeat kinase 2 (LRRK2) is involved in the pathogenesis of Parkinson’s disease (PD)." (PMID 30949397, 2019). "For instance, G2019S and other mutations in the LRRK2 gene have been shown to increase kinase activity, and LRRK2 kinase inhibitors that counteract this activity are currently being tested in phase 1 clinical trials as a potential therapeutic target for Parkinson’s disease." (PMID 31324919, 2019). "We propose that the role of LRRK2 at the lysosome, specifically in regulating lysosomal pH and local calcium release by vATPase a1 binding and trafficking, is a crucial pathological mechanism linking autophagic deficits with Parkinson’s." (PMID 31039583, 2019). "Our findings may have implications for genetic testing where, in the UK, LRRK2 testing is recommended for late-onset patients with a family history of Parkinson’s disease." (PMID 31324919, 2019). "In line with many previous studies, our findings suggest that Parkinson’s disease caused by LRRK2 mutations duplications is clinically indistinguishable from sporadic disease." (PMID 31324919, 2019). "Genetic screening for LRRK2, GBA, and PRKN mutations in patients with Parkinson disease who are candidates for subthalamic deep brain stimulation may serve to inform outcomes." (PMID 30707228, 2019). "The link between the retromer and LRRK2 activity, in the context of Parkinson’s disease, remains unknown." (PMID 30640902, 2019). "Both LRRK2 R1441C carriers reported a family history of Parkinson’s disease." (PMID 31324919, 2019). "A long non-coding RNA promotes MPTP-induced parkinsonism via upregulating the expression of LRRK2." (PMID 29719505, 2018). "The most frequent pathogenic mutation (G2019S) is located within the kinase domain and directly enhances kinase activity, suggesting that LRRK2 inhibitors might offer therapeutic benefit for preventing and treating Parkinson's disease." (PMID 29127256, 2018). "The most common pathogenic mutation lies within the catalytic domain (G2019S) and increases kinase activity, suggesting that LRRK2 inhibitors might offer therapeutic benefit for Parkinson's disease." (PMID 29212815, 2018). "Further, by using dopaminergic neurons derived from patients of familial LRRK2-Parkinson’s disease we report that human RAC1 activity is essential in the regulation of dopaminergic cell death, alpha-synuclein accumulation, participates in neurite arborization and modulates autophagy." (PMID 29429047, 2018). "Nonetheless, we note that knockout of LRRK2 is associated with lung and kidney pathology not seen in animals with knockin of Parkinson disease—associated LRRK2 mutations." (PMID 30571694, 2018). "Our data raise the possibility of a dominant negative, loss-of-function mechanism in LRRK2-related Parkinson disease and thus suggest caution when considering strong or complete inhibition of LRRK2 in therapeutic approaches to the disorder." (PMID 30571694, 2018). "Leucine-rich repeat kinase 2 (LRRK2) is involved in Parkinson’s disease (PD) pathology." (PMID 30460108, 2018).
Parkinson disease (continued). "cis-2,6-Dimethyl-4-(6-(5-(1-methylcyclopropoxy)-1H-indazol-3-yl)pyrimidin-4-yl)morpholine (MLi-2) 178 is a structurally novel, highly potent drug-like compound developed by Merck as a selective Leucine-Rich Repeat Kinase 2 (LRRK2) inhibitor for treatment of Parkinson′s disease (PD)." (PMID 30373212, 2018). "We next explored the feasibility of analysing LRRK2 pathway activity in neutrophils isolated from a small number of Parkinson's patients with and without the G2019S LRRK2 mutation." (PMID 29127255, 2018). "Thus, our results identify a novel role of PINK1 modulating the levels of LRRK2 in Parkinson’s disease fibroblasts and neurons, suggest a convergent pathway for these PARK genes, and broaden the role of LRRK2 in the pathogenesis of Parkinson’s disease." (PMID 27975167, 2018). "Small GTPases are critical modulators of p38 activation and thus, their functional interaction with aSyn and LRRK2 could explain much of the detailed mechanics of autophagy in Parkinson ́s disease." (PMID 30071902, 2018). "Neutrophils were isolated from 13 healthy controls, 7 patients with sporadic Parkinson's and 6 individuals with a heterozygous G2019S LRRK2 mutation — 5 with Parkinson's and 1 non-manifesting carrier." (PMID 29127255, 2018). "The knowledge obtained from such studies not only sheds light on the control of the NFAT pathway, but also could have implications in other diseases associated with LRRK2, such as Crohn’s disease, IBD, and Parkinson’s disease." (PMID 29472933, 2018). "SNP2 (rs11564148) was located in the LRRK2 gene, which is related to Parkinson’s disease." (PMID 28612167, 2017). "Finally, increased predicted bone strength in Lrrk2 null mice is particularly interesting to consider in light of the growing links between Parkinson’s disease and osteoporosis." (PMID 28103901, 2017). "This, and the fact that LRRK2 mutation carriers develop symptoms and brain pathology almost indistinguishable from idiopathic Parkinson’s disease, has led to enormous interest in this protein." (PMID 28103901, 2017). "Unlike other PD-associated genes, LRRK2 Parkinsonism manifests similar clinical phenotypes to idiopathic PD, displaying strong age-dependent development of PD symptoms." (PMID 28202666, 2017). "In the near future, there will be a high demand for central and peripheral pharmacodynamic markers to monitor LRRK2 kinase activity in clinical trials aiming at evaluating the potential of LRRK2 inhibitors as disease-modifying treatment for Parkinson’s disease." (PMID 28860483, 2017). "Interestingly, the striking similarity on the overall structures of LRRK2 and LRRK1 suggests that the specificity of LRRK2 versus LRRK1 in its role in Parkinson’s disease must be sought at another level." (PMID 28819229, 2017). "Concerning Parkinson's disease, Ser(P)- 1292 LRRK2 may be a useful candidate biomarker since its levels were found elevated and correlated with features of Parkinson's disease." (PMID 28912682, 2017). "These disorders include, among others, Parkinson's disease (PD) with SNCA, PINK1, PARK2, GBA1, and LRRK2 mutations, amyotrophic lateral sclerosis (ALS) with TDP43 mutation, Huntington's disease (HD) with HTT mutation, and Spinal muscular atrophy (SMA) with SMN1 mutation." (PMID 27313629, 2016). "Because Parkinson's disease patients show impairments to their striatal dopamine system, we considered whether dopamine transmission might be altered in mutant LRRK2 rats." (PMID 26744332, 2016). "Previous studies have linked mutations in the Lrrk2 but not Lrrk1 gene in humans to Parkinson disease, although both Lrrk1 and Lrrk2 are expressed in multiple tissues including macrophage precursors." (PMID 27600824, 2016).